TPBG (trophoblast glycoprotein)
Description:
May function as an inhibitor of Wnt/beta-catenin signaling by indirectly interacting with LRP6 and blocking Wnt3a-dependent LRP6 internalization.
Synonyms: WAIF1; 5T4; 5T4-AG; 5T4AG; M6P1
Tractability: Small molecule: it belongs to a druggable protein family. Antibody: UniProt places it where antibodies can reach, with high confidence; its Gene Ontology location is reachable by antibodies, with high confidence; UniProt predicts a signal peptide or a membrane-spanning region. PROTAC: ubiquitination databases record sites on it; its protein half-life has been measured. Other modalities: a drug acting on it is in phase 2 or 3 trials.
Target class: Other membrane protein
Gene: Protein-coding gene on chromosome 6 (82,363,206 to 82,367,420, forward strand). Ensembl gene ENSG00000146242.
Subcellular location: Cell membrane
Subcellular location (Human Protein Atlas): Nucleoplasm
Gene Ontology:
Biological process: cell adhesion; negative regulation of canonical Wnt signaling pathway
Cellular component: cell surface; plasma membrane; axon terminus; cytoplasm; dendrite; endoplasmic reticulum
Genetic constraint (gnomAD): Loss-of-function variants: 13 observed, 19.42 expected, observed/expected ratio (o/e) 0.67, 90% interval 0.44 to 1.06. The synonymous counts are far from expectation, so gnomAD's model fits this gene poorly and the ratio says little. Missense variants: 642 observed, 543.45 expected, observed/expected ratio (o/e) 1.18, 90% interval 1.11 to 1.26. Synonymous variants: 338 observed, 256.29 expected, observed/expected ratio (o/e) 1.32, 90% interval 1.21 to 1.44.
Homologues: Orthologues: chimpanzee TPBG (99% identical), macaque TPBG (97% identical), pig TPBG (88% identical), dog TPBG (88% identical), guinea pig TPBG (84% identical), mouse Tpbg (84% identical), rat Tpbg (83% identical), tropical clawed frog tpbg (45% identical), zebrafish tpbg (40% identical), Caenorhabditis elegans iglr-3 (23% identical), Drosophila melanogaster CG7702 (22% identical).